BRCA1 (BRCA1 DNA repair associated)
Diseases named in the same sentence as BRCA1 in open-access papers (continued):
Sharing a sentence is not in itself a finding about the gene and the disease.
Hereditary breast cancer (116 papers, 2001 to 2026). Breast carcinoma that has developed in relatives of patients with history of breast carcinoma. "BRCA1, breast cancer gene 1, known as a tumor suppressor gene, is directly linked with hereditary breast cancer." (PMID 40561071, 2025). "Hereditary breast cancer accounts for 5–10% of all cases, with pathogenic variants in BRCA1/2 and other susceptibility genes playing a crucial role." (PMID 39590369, 2024). "Hereditary breast cancer accounts for 10% of new cases and 4%–5% of cases are associated to pathogenic variants in BRCA1 or BRCA2 genes." (PMID 38414963, 2023). "Germline variants in two high penetrance genes, BRCA1 and BRCA2 (BRCA1/2), are the most common cause of hereditary breast cancer." (PMID 37656691, 2023). "BRCA1 was first discovered by Dr. Mary-Claire King in 1994 and the gene is associated with hereditary breast cancer." (PMID 38137912, 2023). "This almost certainly indicates that even the current reduction in score for lobular breast cancer of -2 is insufficient to reflect BRCA1 risk." (PMID 33763779, 2022). "This was mainly due to late identification of patients with high risk of hereditary breast cancer or delayed prescription of BRCA1/2 mutation testing." (PMID 34285295, 2021). "The unique iMSC model used here was generated using patient-specific iPSCs, which opens new therapeutic avenues for the prevention and personalized treatment of BRCA1-associated hereditary breast cancer." (PMID 33513753, 2021). "Elevated expression of Ang-1, Ang-2 and VEGF was also described in BRCA1/2-mutated tumors of hereditary breast cancer patients." (PMID 33540843, 2021). "The interaction between PALB2 and BRCA2 is important for maintaining genomic integrity.Moreover, BRCA2 and BRCA1 are the most common causes of hereditary breast cancer." (PMID 34092963, 2021). "In BRCA1-associated hereditary breast cancer, the expression of ERβ is significantly higher than that of ERα." (PMID 32944243, 2020). "The breast cancer susceptibility gene 1 (BRCA1) is a major tumor suppressor gene and is most frequently mutated in hereditary breast cancer." (PMID 32195105, 2020). "This review will focus on the surgical and systemic treatment of hereditary breast cancer with a particular focus on BRCA1 and BRCA2 mutations." (PMID 33194613, 2020). "Previous studies in Latin American populations focused mainly on hereditary breast cancer and BRCA1/2 mutations." (PMID 33126731, 2020). "Oxidative stress is involved in mutagenesis, which is a driving force of (breast) cancer initiation and progression, especially in hereditary breast cancer, where the mere loss of BRCA1 increases ROS." (PMID 31835715, 2019). "Hereditary breast cancer commonly results from the presence of a pathogenic germline missense mutation in BRCA1 followed by somatic deletion of the remaining wild-type BRCA1 allele." (PMID 31027346, 2019). "As BRCA1-deficient sporadic triple-negative tumors show the same histological characteristics as BRCA1-related hereditary breast cancers, it has been suggested that BRCA1-deficiency has a role in inducing the triple-negative phenotype." (PMID 28646826, 2018). "Hereditary breast cancer with germline mutations in BRCA1 and BRCA2 genes are characterized by a deficiency in DNA repair mechanisms that renders these tumors sensitive to platinum agents." (PMID 30038706, 2018). "This mutation were functionally characterized as a pathogenic mutation and it was also detected in familial lobular breast cancer patients with the wild type BRCA1/2 gene." (PMID 29050249, 2017). "Forty seven tumors from hereditary breast cancer cases, previously analyzed for BRCA1 expression, and screened for germline BRCA1 and 2 mutations, were analyzed by Array based Comparative Genomic Hybridization (aCGH) using Agilent 4x44K arrays." (PMID 26979459, 2016).
Hereditary breast cancer (continued). "BRCA1 is mutated in approximately 5–10% of hereditary breast cancers and BRCA1 expression is downregulated in up to 40% of sporadic invasive breast carcinomas." (PMID 27589844, 2016). "The BRCA1 gene is directly associated with hereditary breast cancer, and its protein product, BRCA1, is normally expressed in the cells of the breast and other tissues." (PMID 25334066, 2014). "Recently, in France, 16 CHEK2 mutations were found in 507 cases of BRCA1/2-negative hereditary breast cancer." (PMID 24986639, 2014). "BRCA1 dysfunction in hereditary breast cancer causes defective homology-directed DNA repair and sensitivity towards DNA damaging agents like the clinically used topoisomerase I inhibitors topotecan and irinotecan." (PMID 23028879, 2012). "Specific pathological features have been reported in hereditary breast cancer with differences between BRCA1 and BRCA2 associated tumors." (PMID 19619314, 2009). "We demonstrate an association between basal-like and particularly BRCA1 hereditary breast cancer and the presence of CD44+/CD24- cells." (PMID 18559090, 2008). "Hereditary breast cancers linked to germ-line mutations of BRCA1 and BRCA2 genes almost invariably show allelic imbalance (AI) at the respective loci." (PMID 11710835, 2001). "Notably, the BRCA1 PV detected matches a known Saudi founder mutation in hereditary breast cancer, now observed in PTC." (PMID 41898519, 2026). "When BRCA1 mutates, it is associated with the occurrence of hereditary breast cancer." (PMID 36258162, 2022). "Mutations in the BRCA1 gene are known to be a major cause of hereditary breast cancer." (PMID 31998812, 2019). "The IHC test has a very high sensitivity and specificity, and may substantially improve the detection of BRCA1 pathogenetic mutations in families with hereditary breast cancer." (PMID 19818148, 2009). "This distribution underscores the importance of comprehensive multi-gene panel testing beyond BRCA1/2, aligning with recent trends in genetic screening for hereditary breast cancer." (PMID 39590369, 2024). "As such, it has a complementary role alongside BRCA1/2 PVs and is inextricably intertwined with cellular processes that contribute to tumourigenesis in hereditary breast cancer." (PMID 39682099, 2024). "Germline variants in BRCA1 and BRCA2 (BRCA1/2) genes are the most common cause of hereditary breast cancer." (PMID 37656691, 2023). "There are also associations of CPT-1A with the wild-type variants of moderate to highly penetrant genes e.g. BRCA1, BRCA2 and ATM involved in hereditary breast cancer." (PMID 36180554, 2022). "Hereditary breast and ovarian cancer (HBOC) associated with BRCA1 and BRCA2 mutations is the most common form of hereditary breast cancer." (PMID 35742117, 2022). "The probabilities generated by DrABC were distributed differently between non-carriers and patients with GPVs in any CPG (p = 2.0 × 10− 10) or BRCA1/2 (p = 7.8 × 10− 16), suggesting its capability in distinguishing patients with hereditary breast cancer." (PMID 35209950, 2022). "This is in contrast to other types of cancer like hereditary breast cancer, for which BRCA1 and BRCA2 account for more than half of the PVs identified in patients with this diagnosis." (PMID 34255164, 2021). "The top pathways included hereditary breast cancer, role of BRCA1 in DNA damage response, molecular mechanisms of cancer, and ATM and GP6 signalling pathways." (PMID 32724790, 2020). "Of note, we found 16 overlapping pathways in CTCs and metastases primarily involved in the role of BRCA1 in DNA damage response, hereditary breast cancer signaling, ATM signaling, and several others." (PMID 32650480, 2020).
Hereditary breast cancer (continued). "For SNV analysis, we identified 16 overlapping pathways in CTCs and metastases involved in the role of BRCA1 in DNA damage response, hereditary breast cancer signaling, and ATM signaling." (PMID 32650480, 2020). "BRCA1 has a tumor suppressor function related to the transcriptional regulation to maintain genomic stability, which is directly related to hereditary breast cancer." (PMID 31867044, 2019). "The discovery of biological pathways enriched for germline and somatic mutations including the role of BRCA1 in DNA repair, ATM, hereditary breast cancer, and DNA damage checkpoint signaling pathways is of particular interest." (PMID 30909550, 2019). "With the attempt to clearly relate the expression of BRCA1 and the peculiar subcellular localization of HIF-1α and HSP60, the BRCA1 full length was transfected in the hereditary breast cancer model." (PMID 29584711, 2018). "People carrying pathogenic variants of the BRCA1 and BRCA2 genes are often referred to as those having predisposition for ‘hereditary breast cancer’." (PMID 28939999, 2018). "Overall, we demonstrate how clinically relevant changes to BRCA1 affect its structure-function relationship in hereditary breast cancer." (PMID 28262780, 2017). "BRCA1 and BRCA2 are tumor suppressor genes and these mutations were strongly associated with hereditary breast cancer." (PMID 25774336, 2015). "Cancer-related pathways (pancreatic adenocarcinoma signaling, hereditary breast cancer signaling, and role of BRCA1 in DNA damage response) were also highly enriched in the gene list." (PMID 24678894, 2014). "Preclinical and clinical studies in a BRCA1-defective setting have recently indicated a rationale for the use of these compounds against hereditary breast cancers." (PMID 23203101, 2012). "Mutations in the BRCA1 and BRCA2 genes are responsible for only a part of hereditary breast cancer (HBC)." (PMID 22114986, 2011). "BRCA1 plays a crucial role in DNA repair and decreased BRCA1 mRNA has been observed in both sporadic and hereditary breast cancer." (PMID 20209131, 2010). "The BRCA1 and BRCA2 germ-line mutation is known associated with the hereditary breast cancer; and the MMR germ-line mutation (especially hMLH1) for the hereditary nonpolyposis colorectal carcinoma (HNPCC)." (PMID 18973653, 2008). "BRCA1 and BRCA2 genes were identified as causative genes for early-onset hereditary breast cancer." (PMID 33593852, 2021). "A significant percentage of high-risk families with hereditary breast cancer are negative for mutations in BRCA1/2 genes." (PMID 28985766, 2017). "South Americans in general, and specifically Peruvian hereditary breast cancer populations, are not well characterized with mutations in BRCA1 and BRCA2 genes, and a founder effect has not been identified." (PMID 28944232, 2017). "BRCA1 and BRCA2 are among the genes associated with hereditary breast cancer." (PMID 26770289, 2016). "However, mutations in the two major genes, BRCA1 and BRCA2, are found in only 15% to 20% of hereditary breast cancer (HBC) families." (PMID 22114986, 2011). "In this context, it is of interest that BRCA1-defective cells in vitro are resistant to both drugs, suggesting that this treatment might be ineffective in breast hereditary cancer patients." (PMID 12698198, 2003).
Hereditary breast cancer (continued). "Secondly, it will examine the clinical implications of the interactions between BRCA1, and to a lesser extent BRCA2 PVs, the tumour microenvironment, and epigenetic regulation in terms of prognosis and treatment for hereditary breast cancer." (PMID 39682099, 2024). "Multigene panel testing can examine the causative genes of hereditary tumors other than BRCA1/2 efficiently in patients with suspected hereditary breast cancer but who have negative BRCA1/2 genetic test results." (PMID 39831988, 2025). "Given that the BRCA1 gene was identified over 20 years ago, there is a need to identify a novel non-surgical approach to hereditary breast cancer prevention." (PMID 35418083, 2022). "We are not able to stratify for women with hereditary breast cancer, because BRCA1/2 or prophylactic MTX is not recorded in the Cancer Registry." (PMID 25743325, 2015). "The down-regulated genes were primarily clustered in the cell cycle processes (including cell cycle checkpoints, mitotic assembly and DNA duplication), the DNA repair pathways (including BRCA1 in DNA damage response and ATM signaling), protein ubiquitination and hereditary breast cancer signaling." (PMID 23110199, 2012). "To evaluate whether nutlin-3a could serve as a PARP suppressor against BRCA1-associated hereditary breast cancer, we examined the effects of nutlin-3a in MCF-7 cells expressing shRNA against BRCA1 (MCF-7/shBRCA1) or GFP (MCF-7/shGFP), used as a negative control." (PMID 32405340, 2020).
gastric cancer (101 papers, 2008 to 2026). A primary or metastatic malignant neoplasm involving the stomach. "An accumulating body of evidence suggests carriers of a pathogenic germline variant (PGV) in BRCA1 or BRCA2 have increased gastric cancer (GC) risk." (PMID 41256354, 2025). "On the other hand, resistance to ferroptosis has been shown to be induced by BRCA1 deficiency, a gene associated with the risk of developing ovarian, breast, renal cell, and gastric cancers." (PMID 39594843, 2024). "Pathogenic variants in BRCA1/2 have been found to be associated with risks of multiple primary cancers, including pancreatic and stomach cancers." (PMID 36765408, 2023). "We observed that biliary tract, esophageal, and gastric cancer were significantly associated with BRCA1 and/or BRCA2 pathogenic variant status in addition to the 4 established cancer types." (PMID 35420638, 2022). "In recent years, a retrospective multicenter data analysis of gastric cancer with BRCA1 or BRCA2 germline mutations (gBRCAm) was conducted to identify 10 gastric cancer patients with gBRACm, 6 of whom had metastatic disease." (PMID 36035159, 2022). "Stomach cancer represents a significant global cancer burden and BRCA1/2 mutations have been reported to increase the lifetime risk of developing stomach cancer by as much as 6 folds among first-degree relatives of BRCA1/2 mutation carriers." (PMID 35927682, 2022). "Herein, we review the accumulating evidence that suggests BRCA1/2 carriers are at increased risk for gastric cancer, particularly among BRCA2 carriers." (PMID 36497436, 2022). "“Signature 3” is associated with BRCA1/2 mutations and BRCA1 promoter methylation in breast, ovarian, pancreatic, and stomach cancers." (PMID 34722237, 2021). "BRCA1, another hub ageing gene, is associated with breast, ovarian, prostate, pancreas and stomach cancer." (PMID 29340088, 2017). "It was reported that downregulation of BRCA1 nuclear expression was associated with advanced stage and perineural invasion in sporadic gastric cancer." (PMID 27403158, 2016). "It should be underlined that only one BRCA1 (5382insC) mutation was found in the gastric cancer group." (PMID 26779294, 2016). "As a result of the demonstrated contribution of founder BRCA1 mutations in Polish breast/ovarian and other cancers, it seems reasonable to investigate their role in gastric cancer cases." (PMID 26779294, 2016). "Both cases of BRCA1 mutation carriers were men (56 and 47 years old) and they both had intestinal, advanced gastric cancer located in body." (PMID 26779294, 2016). "Confirmed associations of BRCA1/2 gene mutations with prostate, pancreatic and stomach cancer at a population level have been reported within the research." (PMID 26236408, 2015). "Analysis of the literature identified a number of studies implicating mutated BRCA1/2 genes were responsible for a significant fraction of prostate, pancreatic and stomach cancer development, as well as susceptibility to advanced disease." (PMID 26236408, 2015). "This review examines the association of BRCA1/2 germline gene mutations with prostate, pancreatic and stomach cancers." (PMID 26236408, 2015). "Stomach cancer represents a significant global cancer burden and BRCA1/2 mutations have been reported to increase the lifetime risk of developing stomach cancer by as much as 6-fold greater among first-degree relatives of BRCA1/2 mutation carriers." (PMID 26236408, 2015). "We have previously observed that BRCA1 mRNA levels in effusions were negatively associated with platinum sensitivity but positively associated with docetaxel sensitivity in gastric cancer patients." (PMID 25496700, 2014). "BRCA1 and TS mRNA levels in both plasma and tumor were associated with in vitro chemosensitivity of freshly explanted gastric cancer." (PMID 25496700, 2014).